IL22 (interleukin 22)
Diseases named in the same sentence as IL22 in open-access papers (continued):
Sharing a sentence is not in itself a finding about the gene and the disease.
pancreatic cancer (16 papers, 2013 to 2025). "Particularly, IL-22-producing cells are associated with various human diseases, including several malignancies, such as lung, liver, gastric, colon, and pancreatic cancers, showing elevated IL-22 levels." (PMID 40806452, 2025). "In pancreatic cancer, IL-22 enhances metastatic ability of pancreatic ductal adenocarcinoma cell lines, and high expression of IL-22 and IL-22R1 was associated to poor prognosis." (PMID 25793261, 2015). "Co-culture experiments demonstrated that ILC3s isolated from human pancreatic cancer tissues promote the proliferation, invasion, and migration of pancreatic cancer cell lines via IL-22/IL-22R-AKT signaling, leading to the progression of the pathology." (PMID 36341381, 2022). "In pancreatic cancer, the IL-22 secreted by innate immune cells activates the AKT signaling pathway to promote tumor metastasis." (PMID 35669104, 2022). "Analogous to other cancer types, pancreatic cancer tissues showed increased IL-22 secretion level being ILC3s the main source of this cytokine." (PMID 36341381, 2022). "Interleukin-22 (IL22): IL22 has been recently identified as a pro-tumorigenic cytokine in pancreatic cancer." (PMID 34771695, 2021). "In pancreatic cancer, IL-22 promoted pancreatic cancer stemness via IL22RA1/STAT3 signalling, establishing the mechanism of regulation of cancer stemness in the tumour microenvironment." (PMID 34572431, 2021). "IL-22 has been shown to increase the tumorigenicity and stemness of pancreatic cancer cells, through JAK/STAT3 signaling." (PMID 33042126, 2020). "In gastric and pancreatic cancer, increased intratumoral IL-22 producing CD4+ T cells correlated with disease's progression and predicted poor patient survival." (PMID 27489357, 2016). "Most recently, IL-22 demonstrated pro-tumoral activity in human pancreatic cancer cell line via inducing the expression of vascular endothelial growth factor (VEGF) and anti-apoptotic factor Bcl-XL." (PMID 23667456, 2013). "For example, one study showed the presence of IL-22 producing ILCs in pancreatic cancer, which increased binding to IL-22R in pancreatic tissue and resulted in AKT signaling, which contributed to proliferation, invasion, and migration of cancer cells throughout tumorigenesis." (PMID 35628427, 2022). "Likewise, through STAT-3 dependent up-regulation of MMP9, in vitro IL-22 has been shown to enhance the metastatic potential of pancreatic cancer cell lines." (PMID 33042126, 2020). "A specific example of this would be in the pancreas, where IL-22 is known to promote repair and renewal of pancreatic acinar cells during injury, but may also lead to the development of pancreatic carcinoma when dysregulated." (PMID 33003458, 2020). "In pancreatic cancer cell lines, production and release of various tumor enhancing factors including VEGFα, Interleukin 10 and TGF-β are stimulated by IL-22." (PMID 33042126, 2020).
Granuloma (15 papers, 2010 to 2023). A compact, organized collection of mature mononuclear phagocytes, which may be but is not necessarily accompanied by accessory features such as necrosis. "For example, CD patients with granuloma are reported to have increased frequencies of IL-22+ and IL-22+ IFN-γ+ cells in colonic tissue." (PMID 36769019, 2023). "The study reported upregulation of IL-22 in bTB lymph node lesions with a clear trend of decreasing mRNA expression from granulomas in early to advanced stages, indicating the potential of IL-22 as a biomarker for bTB pathology." (PMID 33746980, 2021). "For example, CD patients with granuloma are reported to have increased frequencies of IL-22+ and IL-22+IFN-γ+ cells colonic tissue." (PMID 31906479, 2020). "Consistently, IL-22-producing T cells were visualized in situ in lung TB granulomas, indicating that mature IL-22-producing T cells were present in TB granuloma." (PMID 21253470, 2011). "Furthermore, increased CD3 + IL-22+ cells have been described in lung and granulomas of rhesus macaques following Mtb infection." (PMID 37898618, 2023). "Increases in serum IL-17 and IL-22 levels are related to granuloma formation in sarcoidosis." (PMID 37179316, 2023). "IL-22-producing T cells were most frequent in lungs, and involved in TB granuloma formation." (PMID 20195465, 2010). "More importantly, in situ studies using confocal microscopy and immunohistochemistry can readily detect these IL-22-producing T cells in lung tissue sections and granulomas from infected monkeys, indicating that IL-22-producing T cells are present in TB granulomas or lesions." (PMID 20195465, 2010). "IL-22 has also been shown to induce smoking-dependent airway remodeling and emphysema-like alveolar enlargement in chronic obstructive pulmonary disease, as well as the recruitment, activation, and proliferation of mononuclear cells, contributing to alveolitis and granuloma formation in sarcoidosis." (PMID 35163689, 2022). "IL-22 has been suggested to play a protective role in the disease by inhibiting CD4+ T cell migration and collagen deposition and the decrease in IL-22 in the TLR2/9-/- mice may explain the development of granulomas despite decreased T cell activation and TNFα production in these mice." (PMID 24023674, 2013). "In spite of microscopic morphological similarities, significant differences were seen between late stage granulomas of the lung compared to those of the tracheobronchial lymph nodes for IL-17A, IFN-γ, TGF-β, IL10 and IL-22 but not for TNF-α." (PMID 27902779, 2016). "Additionally, significant differences were noted between granulomas from two different thoracic lymph nodes that both receive afferent lymphatics from the lungs (i.e., tracheobronchial and caudal mediastinal lymph nodes) for TNF-α, IL-17A, IFN-γ, TGF-β and IL-10 but not for IL-22." (PMID 27902779, 2016).
Hyperglycemia (15 papers, 2015 to 2025). An increased concentration of glucose in the blood. "IL-22 released by ILC3 cells protected pancreatic islet beta cells from inflammation and glucotoxicity, potentially reversing the damage caused by hyperglycemia to pancreatic islet beta cells, thus improving insulin sensitivity." (PMID 39944639, 2025). "They found attenuation of the upregulation of LIGHT receptors (LTβR and HVEM) that occurred in engrafted human islets exposed to hyperglycemia by IL-22." (PMID 40422866, 2025). "The development of hyperglycemia with age in the IL-22ra1ΔβKO animals suggests that IL-22 signaling is protective and prevents the age-related decline of beta-cell function and number." (PMID 38811550, 2024). "Serum glucose values were measured to assess the effect of anti-ANGPTL3/IL22 fusion protein treatment on hyperglycemia." (PMID 36544775, 2022). "Meanwhile, therapeutic effects of IL-22 gene therapy were apparent despite initiation of treatment 17 weeks after persistent hyperglycemia and nephropathy onset, reflecting at least partial disease reversal by targeting renal NLRP3 inflammasome." (PMID 28726774, 2017). "IL-22 is involved in the regulation of a variety of chronic inflammatory diseases and, in numerous instances, diseases related to glucose metabolism abnormalities, such as hyperglycemia and IR, can be controlled and alleviated through the exogenous infusion of artificial IL-22 in obese mice." (PMID 40357203, 2025). "This suggests that IL-22 signaling, and not IL-20 or IL-24 signaling, is associated with hyperglycaemia." (PMID 38811550, 2024). "Therefore, hyperglycemia stimulates T cells and T cell-derived products, including IL-1, IL-6, IL-17, and IL-22, which are of central importance in progressive fibrosis in DKD." (PMID 36776877, 2023). "In addition, IL-22 gene therapy markedly attenuated hyperglycemia and metabolic disorders in streptozotocin-induced experimental diabetic mice." (PMID 28726774, 2017). "Notably, we reported for the first time that IL-22 gene therapy not only suppressed the systemic pathogenesis of DN, including hyperglycemia and metabolic disorders, but also protected against renal pathogenesis via suppression of NLRP3 inflammasome activation." (PMID 28726774, 2017). "It has been universally recognized that simply targeting systemic hyperglycemia and metabolic disorders is not sufficient to arrest the progression of DN,8, 40, 41, 42, 43 indicating that there must be other molecular mechanism responsible for therapeutic effects of IL-22 for DN." (PMID 28726774, 2017).
alcoholic hepatitis (14 papers, 2013 to 2025). Acute hepatitis resulting from ingestion of alcohol. "IL-22 was then administered to alcohol-fed mice to test its protective effects on alleviating alcoholic hepatitis, focusing on intestinal protection." (PMID 37908362, 2023). "F-652, an IL-22-based biopharmaceutical agent, was recently shown to be effective in a phase II clinical trial addressing patients with alcoholic hepatitis." (PMID 34638962, 2021). "Both trials implicate IL-22 in alcoholic hepatitis, with the first studying its biological effects in the disease and the second aiming to use recombinant human IL-22 to take advantage of the anti-steatotic and anti-apoptotic functions of this cytokine." (PMID 29892294, 2018). "Those patients who markedly improved their Glasgow Alcoholic Hepatitis Score demonstrated a 2-fold higher frequency of IL-22-producing T helper cells at baseline and during follow-up than patients whose condition deteriorated (p = 0.04)." (PMID 23372820, 2013). "We look forward to the results of these clinical trials and hope that IL-22 therapy may benefit some patients with severe alcoholic hepatitis." (PMID 32760208, 2020). "Administration of IL-22 combine with steroid may be beneficial in the treatment of severe alcoholic hepatitis as IL-22 can negate the side effects of hormone therapy and contribute to the regeneration of the liver." (PMID 32760208, 2020). "Roche together with Genentech (RG7880, UTTR1147A) and Generon (Promenakin, F-652) develop IL-22 agonists for the treatment of ulcerative colitis with ongoing trials also in pancreatitis, acute alcoholic hepatitis, graft versus host disease and treatment of diabetic foot ulcers." (PMID 30319661, 2018). "Further, T cell differentiation toward an IL-22-producing phenotype may also be favorable in alcoholic hepatitis." (PMID 30319661, 2018). "However, the intestinal role of IL-22 in alcoholic hepatitis remains to be elucidated." (PMID 37908362, 2023). "In alcoholic hepatitis patients whose condition seemed to improve, the frequency of IL-22-producing T helper cells was found to be increased, indicating T cell differentiation toward an IL-22-producing phenotype might be favorable for ALD suppression." (PMID 31244862, 2019). "The long-circulating IL-22 fusions improved MELD (Model of End-Stage Liver Disease) and Lille scores in patients with alcoholic hepatitis following twice weekly i.v." (PMID 38811532, 2024). "IL-22 also acts as a crucial mediator of the hepatoprotective effects of TLR-7 agonistic agent (1Z1) and functions by promoting the expression of antimicrobial peptides (Reg3b and Reg3g) and modulating the intestinal microbiome in an alcoholic hepatitis mouse model." (PMID 34944732, 2021). "Furthermore, hepatic expression of IL-22R1 was upregulated in patients with alcoholic hepatitis without elevation of IL-22, suggesting that these patients may be sensitive to IL-22 treatment." (PMID 24623532, 2014).
plaque psoriasis (14 papers, 2015 to 2025). "One report on the PE lesions of plaque psoriasis patients caused by IL-17 inhibitors suggested that IL-22 plays a significant role in PE development." (PMID 39149635, 2024). "Exon 1 of IL22 contains a CNV previously associated with psoriasis vulgaris." (PMID 30779748, 2019). "Cytokine dynamics in the patient's serum suggest the involvement of IL-22 in the development of PE, as in plaque psoriasis." (PMID 39149635, 2024). "The aim of this study was the assessment of IL-22 levels and its correlation with disease activity in plaque psoriasis." (PMID 30291393, 2019). "At present, biologics directed against the cytokines TNFα, IL-17, IL-22, and IL-12/23 have been approved for the treatment of moderate-severe plaque psoriasis by the FDA and EMA31." (PMID 29515113, 2018). "In conclusion, curcumin was demonstrated to be effective as an adjuvant therapy for the treatment of psoriasis vulgaris and to significantly reduce serum levels of IL-22." (PMID 26090395, 2015). "Targeting IL-22 may have promise as a potential therapeutic agent for plaque psoriasis." (PMID 30291393, 2019). "Targeting IL-22 may be promising as a potential therapeutic for plaque psoriasis." (PMID 30291393, 2019). "Increased serum levels of TNF-α, IL-17, IL-22, and IFN-γ have been detected in patients with PPP in comparison to healthy subjects, suggesting a similar inflammatory pattern to psoriasis vulgaris." (PMID 34409425, 2021). "Considering apremilast’s role in reducing IL-17F, IL-17A, IL-22, and TNF-α plasma levels in patients with moderate to severe plaque psoriasis, it could be hypothesized that apremilast acts as a pleiotropic molecule, blocking a common pathway shared by both PsO and MetS." (PMID 39204094, 2024). "Therefore, cytokines such as IL-17A, IL-22, IL-23, and TNF-α were found to be elevated in both psoriasis vulgaris and GPP; however, GPP lesions yielded significantly higher IL-1 and IL-36, and lower IL-17A and interferon-gamma (IFN-γ) messenger RNA (mRNA) expressions, than plaque psoriasis lesions." (PMID 34445754, 2021).
psoriatic arthritis (14 papers, 2012 to 2024). Joint inflammation associated with psoriasis. "In patients with psoriatic arthritis, high levels of IL-23 and IL-17A are present in the synovium, and tissue-retained Th17 cells highly express IL-22 and IL-17A." (PMID 37920459, 2023). "Patients with psoriatic arthritis often have resident Th17 cells within the synovium that overexpress IL-17A and IL-22, exacerbating inflammation and bone reconstruction." (PMID 37920459, 2023). "In the case of psoriatic arthritis, IL‐36 activates dendritic cells inducing Th17 cells to generate IL‐17 and IL‐22, resulting in persistent arthritis." (PMID 37469370, 2023). "Upregulation of RORγt and elevated levels of IL-17A and IL-22 producing tissue-resident memory CD8 positive T cells have been observed in skin from patients with psoriatic arthritis." (PMID 35337918, 2022). "Increased frequency of CD4+IL-17+ cells, but decreased frequency of CD4+IL-22+ T cells, in psoriatic arthritis synovial fluid compared to peripheral blood." (PMID 24286492, 2013). "Here we are reporting the functional role of IL-22 in the inflammatory and proliferative cascades of psoriatic arthritis (PsA)." (PMID 22417743, 2012). "Here, we examined the role of IL-22 in patients with psoriatic arthritis (PsA)." (PMID 29163483, 2017). "Thus, IL-22/IL-22R system may be a potential novel target of drug development for psoriatic arthritis." (PMID 22417743, 2012). "The pathogenesis of psoriatic arthritis is related to the innate and adaptive immune response involving different proinflammatory cytokine, including TNF, IL-1β, IL-6, IL-22, IL-23, IL-17A, and IL-18." (PMID 36297574, 2022).
sarcoidosis (14 papers, 2012 to 2023). Sarcoidosis is a multisystemic disorder of unknown cause characterized by the formation of immune granulomas in involved organs. "A few studies have analyzed the roles of the Th17 effector cytokines IL-17A/F, IL-21, and IL-22 in the pathogenesis of sarcoidosis." (PMID 26845566, 2016). "A few studies have analyzed the role of the Th17 effector cytokines IL-17A/F, IL-21, and IL-22 in sarcoidosis, but the results are contradictory." (PMID 25386143, 2014). "If the top marker (IL22) is removed from the list, incorrect predictions are observed even using all remaining markers; therefore, phenotyping sarcoidosis vs Behçet's is inherently high-dimensional (since it requires at least 5 markers to be accurate) and also very specific to those markers." (PMID 24039568, 2013). "Vitreous levels of IL-4, IL-17A, IL-22, IL-31, and TNFα in PDR patients were also significantly higher than those of sarcoidosis patients." (PMID 26352837, 2015). "A protective anti-inflammatory effect of IL-22 has been demonstrated in the case of pulmonary inflammation, with lower levels being detectable in the bronchoalveolar lavage fluid (BALF) of patients with acute respiratory distress syndrome and sarcoidosis." (PMID 37753072, 2023). "In skin lesions of sarcoidosis patients, IL-21 has been found to be elevated, whereas IL-17 and IL-22 were not dysregulated." (PMID 25386143, 2014). "The level of IL-22 in BE (75.3 ± 122.2 pg/ml, 75%) was respectively about 17-fold, 16-fold, 1500-fold, and 9.7-fold higher than that in ERM (4.54 ± 7.73 pg/ml, 53%), IOL (4.77 ± 5.60 pg/ml, 46%), sarcoidosis (0.05 ± 0.18 pg/ml, 7%), and ARN (7.75 ± 26.3 pg/ml, 15%)." (PMID 32066796, 2020).
helminth infection (13 papers, 2012 to 2023). "Multiple attempts have been made to understand the association between helminth infections and IL-22 as a central mediator of the host’s immune response in the gut and the liver." (PMID 33851257, 2021). "Ang4, Clca1, and Retnlb are goblet-cell associated genes that are induced during immune responses, such as bacterial and helminth infections, and are typically stimulated by type 2 and 3 immune cytokines such as IL-4/IL-13 (type 2) and IL-22 (type 3)." (PMID 37869014, 2023). "In a study on IL-22-KO mice intestines, the increase in goblet cell number and muc2 expression was suppressed upon intestinal helminth infection." (PMID 34759916, 2021). "Taken together these observations suggest that in helminth infections IL-22 signalling plays a relatively minor role in worm expulsion." (PMID 30640950, 2019). "To date, only a few studies have attempted to address the role of IL-22 in the context of helminth infection." (PMID 25360134, 2014). "However, further studies are needed to determine the role of IL-22 in helminth infections." (PMID 33851257, 2021). "While helminth infection clearly induces IL-22, so far no role for Th22 in either immune-mediated protection or pathology has been proven." (PMID 25360134, 2014).